CAND2 (cullin associated and neddylation dissociated 2 (putative))
Description:
Probable assembly factor of SCF (SKP1-CUL1-F-box protein) E3 ubiquitin ligase complexes that promotes the exchange of the substrate-recognition F-box subunit in SCF complexes, thereby playing a key role in the cellular repertoire of SCF complexes.
Synonyms: KIAA0667; TIP120B; Tp120b
Tractability: PROTAC: UniProt records ubiquitination sites on it; ubiquitination databases record sites on it; its protein half-life has been measured.
Gene: Protein-coding gene on chromosome 3 (12,796,472 to 12,834,818, forward strand). Ensembl gene ENSG00000144712.
Subcellular location: Nucleus
Subcellular location (Human Protein Atlas): Nuclear bodies; Cytosol
Gene Ontology:
Molecular function: protein binding; TBP-class protein binding
Biological process: positive regulation of DNA-templated transcription; protein ubiquitination; SCF complex assembly
Cellular component: cytosol; nucleus
Genetic constraint (gnomAD): Loss-of-function variants: 60 observed, 91.25 expected, observed/expected ratio (o/e) 0.66, 90% interval 0.53 to 0.81. The upper end of that interval is the gene's LOEUF score, 0.81, which puts it in group 3 of 6, group 1 being the genes least tolerant of losing a copy. Missense variants: 1,497 observed, 1,618.3 expected, observed/expected ratio (o/e) 0.93, 90% interval 0.89 to 0.96. Synonymous variants: 766 observed, 711.52 expected, observed/expected ratio (o/e) 1.08, 90% interval 1.01 to 1.14.
Homologues: Orthologues: chimpanzee CAND2 (99% identical), dog CAND2 (95% identical), macaque CAND2 (95% identical), pig CAND2 (95% identical), rabbit CAND2 (93% identical), rat Cand2 (91% identical), mouse Cand2 (91% identical), guinea pig CAND2 (87% identical), Drosophila melanogaster Cand1 (52% identical), Caenorhabditis elegans cand-1 (35% identical). Paralogues in human: CAND1 (63% identical).
Diseases named in the same sentence as CAND2 in open-access papers:
CAND2 is named in the same sentence as 22 diseases in open-access papers, as found by Europe PMC text mining. Sharing a sentence is not in itself a finding about the gene and the disease. The quoted sentences say what the papers report.
atrial fibrillation (4 papers, 2016 to 2022). A disorder characterized by an electrocardiographic finding of a supraventricular arrhythmia characterized by the replacement of consistent P waves by rapid oscillations or fibrillatory waves that vary in size, shape and timing and are accompanied by an irregular ventricular response. "While the role of CAND2 in regulating CRLs has not been well elucidated yet, population genetics and genome-wide association studies have identified CAND2 as a risk factor for multiple types of cardiovascular diseases (especially atrial fibrillation)." (PMID 35327608, 2022). "Both ALPK3 and VCL are associated with cardiomyopathy, and CAND2 is associated with atrial fibrillation and also creatine kinase concentrations." (PMID 33961016, 2021). "Although expressed to a lower amount in cardiac tissues, Cand2 has been implicated in genome-wide association study (GWAS) analyses as a candidate gene for atrial fibrillation susceptibility." (PMID 33114658, 2020). "However, targets of Cand2 action in the heart that are causative of the atrial fibrillation phenotype remain unknown." (PMID 33114658, 2020).
clubfoot (2 papers, 2018 to 2024). The most common congenital deformation of the foot, occurring in 1 of 1,000 live births. "Initially, genes associatedwith clubfoot (PITX1, TBX4, HOXA9, HOXD10, HOXD12,HOXD13, HOXA9, TPM1, TPM2, COL9A1, FLNB, CASP8,CASP10, UTX, CHD1, RIPPLY2, CAND2, WNT7) werescreened for potential variants." (PMID 38952703, 2024). "They genotyped the CAND2 gene in 256 clubfoot patients and 75 control patients, while Wnt7a was screened using 56 clubfoot patients and 50 control patients." (PMID 30134936, 2018).
cerebral cavernous malformation (1 paper, 2022). A disorder characterized by malformations in the structure of the capillaries in the brain. "CAND2, which encodes cullin-associated and neddylation-dissociated 2, plays a role in cerebral cavernous malformations." (PMID 35733147, 2022).
Hypertension (1 paper, 2024). The presence of chronic increased pressure in the systemic arterial system. "Two of the recurrent AF genes also code for functions directly or indirectly linked to AF (CASQ2 and GOSR2), and some genes indicate a possible indirect link related to comorbidities, e.g., hypertension or malignancy (PPFIA4, USP34, WIPF1, SPATS2L, CAND2, and AOPEP)." (PMID 38725839, 2024).
leukemia (1 paper, 2024). A malignant (clonal) hematologic disorder, involving hematopoietic stem cells and characterized by the presence of primitive or atypical myeloid or lymphoid cells in the bone marrow and the blood. "Satb1 has previously been shown to be associated with heightened hematopoietic stem cell (HSC) self-renewal, whereas the role of Tubb2a, Cnn3, Nedd4, and Cand2 in hematopoiesis and/or leukemia is poorly described." (PMID 38555405, 2024).
Obesity (1 paper, 2023). Accumulation of substantial excess body fat. "CAND2 has also been identified as a novel obesity susceptibility gene." (PMID 37627046, 2023).
ovarian carcinoma (1 paper, 2023). A malignant neoplasm originating from the surface ovarian epithelium. "We carried out differential gene expression analysis between ovarian cancer and healthy ovarian tissues for each cell population, and found that C1orf60, TRABD2A, CAND2 and other genes were significantly up-regulated genes in multiple clusters." (PMID 37124501, 2023).
Stroke (1 paper, 2022). Sudden impairment of blood flow to a part of the brain due to occlusion or rupture of an artery to the brain. "Furthermore, we identified ICA1L, CAND2, and ALDH2 from comprehensive analyses, including non-lacunar stroke brain PWAS and colocalization, and ICA1L was supported at the brain transcriptional level." (PMID 35733147, 2022).
Tumor (1 paper, 2024). "However, for the Mediate the Crosstalk Between Tumor Intermediate State and the T Exhausted State pathway, the C0 CAND2+ TCs and C3 TEX41+ TCs, G1 Phase, and Neoadjuvant had higher expression levels." (PMID 39136009, 2024).
CAND2 also shares sentences with these, for which no sentence is quoted: breast carcinoma (1 paper); Cachexia (1); cancer (1); cardiomyopathy (1); cardiovascular diseases (1); diabetes (1); dilated cardiomyopathy (1); Insulin resistance (1); prostate carcinoma (1); prostate tumors (1); renal cell carcinoma (1); schizophrenia (1); type 2 diabetes (1).